GDNF (glial cell derived neurotrophic factor)
Diseases named in the same sentence as GDNF in open-access papers (continued):
Sharing a sentence is not in itself a finding about the gene and the disease.
depression (continued). "The aim of the present study was to investigate any possible association of the GDNF gene polymorphisms with non-clinical individual variations of anxiety and depression." (PMID 24324616, 2013). "Association results for the 8 GDNF SNPs are represented in each row with the number of detected alleles, calculated MAF values, mean and standard deviation of anxiety and depression scores for carriers of the presented alleles and the corresponding p values from the ANCOVAs." (PMID 24324616, 2013). "In light of these findings and given the critical role ascribed to GDNF in the development and function of hippocampal cells, it is possible that alterations of GDNF are relevant for the “plasticity deficit” that appears in depression." (PMID 24312008, 2013). "Analysis of GDNF level changes in depressive disorders revealed contradictory results." (PMID 24324616, 2013). "Also the neurotrophin-3 (NT-3), GDNF and artemin (member of the GDNF family) were found to have decreased mRNA expression in the blood of patients with major depression." (PMID 22654714, 2011). "In addition, GDNF may be decreased in the peripheral blood of patients with major depressive disorder." (PMID 40642294, 2025). "Thus, a reduction in the GDNF level in LF might be one of potential biomarkers of both depression and epilepsy." (PMID 38069144, 2023). "Therefore, the upregulations of P75 and GDNF at the same time in the male rats may play a neuroprotective role against stress-induced depression, which deserves further study." (PMID 36703721, 2022). "Furthermore, the lower expression of GDNF and its receptors in females may be another factor that contributes to female vulnerability to the onset of depression." (PMID 36703721, 2022). "Hence, the interaction between dysregulation of BBB and neurotrophic levels of GDNF might play a role in the pathogenesis of depression." (PMID 34078872, 2021). "Thus far, the exact involvement of GDNF in the etiology of depression is not fully understood, but its neuroprotective capacity might make it an interesting future target for antidepressant treatment." (PMID 29961124, 2018). "Recent studies indicate a possible diagnostic value of plasma GDNF levels in depression, but whether GDNF and related Ca2+/GABA mechanisms may play prominent role in the development and progression of PD-related depression is unclear at the moment (Ibáñez and Andressoo, 2016)." (PMID 27375426, 2016). "Thus, similar to the case of BDNF, it appears that the relationship between GDNF and depression may be more nuanced and complex than perhaps initially thought, and compensatory processes are likely involved." (PMID 24312008, 2013). "There are also studies that use focused ultrasound combined with GDNF-loaded MBs to open the BBB and release it in a targeted manner to treat depression in rats." (PMID 41155887, 2025). "Previous studies have utilized focused ultrasound in conjunction with GDNF-loaded MBs to transiently open the BBB and alleviate depression in rats." (PMID 41155887, 2025). "In conclusion, this study identified significant differences in serum BDNF, GDNF, 5-HT, and IL-1β among the HC, PWE, and PWECD groups, suggesting their involvement in epilepsy and comorbid depression." (PMID 39474368, 2024). "Chronic stress enhances the function of HDAC2, which inhibits the transcription of glial cell-derived neurotrophic factor (GDNF) and thus induces depression; abnormal expression of HDAC4/5 and subsequent abnormal acetylation of histones leads to depression." (PMID 37140907, 2023). "It is thus not surprising that the focus of the pharmacological study on phytochemicals for the treatment of depression has been targeting neurotrophic factors, among which BDNF, GDNF, VEGF, and NGF are the most relevant neurotrophins." (PMID 37089920, 2023).
depression (continued). "The results obtained confirm the involvement of the HPA axis, the system of neurotrophic factors (GDNF, BDNF), and inflammation (TNF-α) in the pathogenesis of epilepsy and depression." (PMID 38069144, 2023). "Some scholars have found that GDNF and mRNA are closely related to PSD, and GDNF can be used as a biomarker for the differential diagnosis of major depression and PSD." (PMID 38020612, 2023). "The decreased concentrations of BDNF, glial cell line-derived neurotrophic factor (GDNF), Artemin (ARTN), nerve growth factor (NGF), and vascular endothelial growth factor (VEGF) are a good repetitive finding in depression." (PMID 35369081, 2022). "The severity of clinical symptoms was assessed by Hamilton Depression scale (HAMD-17) and Hamilton anxiety scale (HAMA-17) in patients with MDD and HC, and the differences of glial cell line-derived neurotrophic factor (GDNF) levels among different subgroups were compared." (PMID 34531719, 2021). "The data suggested that decreased expression levels of BDNF, GDNF, and NGF were concordant with the increased anxiety and depression-like behaviours in aged male mice offspring conceived by ART." (PMID 34605773, 2021). "In this study, both BDNF and GDNF decreased by 21 d stress, indicating that CUMS successfully induced depression in a mouse model." (PMID 28348623, 2017). "Consistently, antidepressant reduces the recruitment of HDAC4 to the glial cell-derived neurotrophic factor (GDNF) promoter, consequently increasing the expression of GDNF which is reduced in patients with depression." (PMID 27847464, 2016). "The expressions of glial cell-derived neurotrophic factor (GDNF) and brain-derived neurotrophic factor (BDNF) are also regulated by stress-related mood disorder and depression." (PMID 23878590, 2013). "The Self-Rating Depression Scale (SDS) score negatively correlated with serum 5-HT and GDNF levels." (PMID 39474368, 2024). "Decreased serum BDNF levels correlate with epilepsy but not necessarily with comorbid depression, while serum GDNF and 5-HT show potential clinical value in diagnosing this comorbidity." (PMID 39474368, 2024). "In addition to BDNF, changed levels of glial cell line-derived neurotrophic factor (GDNF), vascular endothelial growth factor (VEGF), and NGF in the depression brains were reported." (PMID 37781095, 2023). "Another study of depression in adolescent patients discovered increased BDNF but no changes in NGF or GDNF." (PMID 35431783, 2022). "GDNF and NGF were significantly downregulated in the hippocampus and PFC, which might contribute to increase the anxiety and depression levels in the offspring from IVF-ET and IVF-FET groups." (PMID 34605773, 2021). "GDNF serum level did not correlate with metabolic parameters except for total cholesterol in depression." (PMID 31853432, 2019). "Similarly, in a study examining subjects with depression, melatonin safeguarded hippocampal neurons from damage via BDNF or glial cell-derived neurotrophic factor activation." (PMID 31824318, 2019). "In contrast, the protein levels of GDNF and its receptor GFRA1 were reduced in depression." (PMID 29617307, 2018). "Conclusion: up-regulation of DNA methylation at the GDNF gene promotor and the subsequent down-regulation of the GDNF gene expression in the VTA, may be involved in the development of depression-like behaviors in rats experiencing MD in early life." (PMID 30728784, 2018). "However, plasma GDNF levels were elevated in euthymic patients with MDD and in patients with late-onset depression." (PMID 28348623, 2017). "On the other hand, a recent post mortem analysis of human brain samples disclosed elevated GDNF protein levels in the parietal cortex but not in limbic areas and basal ganglia of patients with depressive disorder." (PMID 24324616, 2013).
depression (continued). "However, after controlling for factors such as sex, age, BMI, estimated IQ, and diagnosis, serum GDNF levels in BD patients were lower in remission and depression states than HCs (this did not occur in patients in a manic or mixed state)." (PMID 38758506, 2024). "In this study, we revealed the significant differences in serum BDNF, GDNF, 5-HT, and IL-1β among the HC, PWE, and PWECD groups, along with the negative correlation with depression severity in serum GDNF and 5-HT levels, supporting their role in epilepsy and comorbid depression." (PMID 39474368, 2024). "In conclusion, up-regulation of the DNA methylation at the GDNF gene promotor and the subsequent down-regulation of the GDNF gene expression in the VTA, may be involved in the development of depression-like behaviors in rats experiencing maternal deprivation in early life." (PMID 30728784, 2018). "In addition to BDNF, other trophic factors, including glial derived neurotrophic factor (GDNF) and fibroblast growth factor (FGF-2), might also play a role in depressive disorders." (PMID 24019878, 2013). "Nonetheless, according to the neurotrophic hypothesis, depression could be the result of the stress-induced reduced expression of neurotrophic factors such as Brain-Derived Neurotrophic Factor (BDNF), IGF-1 or Glial cell line-derived neurotrophic factor (GDNF)." (PMID 37894932, 2023). "However, in the present study, depression did not influence the GDNF content either in LF or BS." (PMID 38069144, 2023). "Furthermore, we developed GDNF-loaded microbubbles (MBs) and achieved local and precise delivery of GDNF to the CNS through MRI-guided focused ultrasound-induced BBB disruption, and confirmed its therapeutic effects on chronic mild stress rat model of depression." (PMID 36046678, 2022). "Furthermore, the methylation level of the GDNF gene correlated with anhedonia and locomotor activity, suggesting that a high level of DNA methylation in the GDNF gene in the VTA, may be one of the regulatory mechanisms of maternal deprivation-induced adult depression in rats." (PMID 30728784, 2018). "A possible explanation for non-decreased GDNF in PSD is that transient focal ischemia and reperfusion in stroke stimulated the expression of GDNF and its receptors GFR-α1 and c-Ret30, and this may counteract the descent of GDNF in the chronic stress caused by depression." (PMID 28819313, 2017). "However, some studies have shown that serum levels of GDNF, NGF, and NTF3 in patients with major depression are not significantly different." (PMID 37509026, 2023).
Stroke (84 papers, 2007 to 2025). Sudden impairment of blood flow to a part of the brain due to occlusion or rupture of an artery to the brain. "The intra-cerebral injection of the HIRMAb-GDNF fusion protein caused a 77% reduction in hemispheric stroke volume in the MCAO model in rats." (PMID 38035276, 2023). "GDNF has been shown to promote neurogenesis and has been associated with the beneficial effects of exercise in stroke recovery." (PMID 30034335, 2018). "The present study demonstrated that DADLE, possibly by increasing GDNF expression in critical brain regions, prevented cell death processes and behavioral abnormalities associated with experimental stroke in rats." (PMID 19534760, 2009). "For example, higher concentrations of aquaporin-4 and glial-cell-line-derived neurotrophic factor (GDNF) in astrocyte-derived EVs have been correlated with stroke severity and clinical outcome." (PMID 41010360, 2025). "Gut microbiota also influences neurotrophic factors such as brain-derived neurotrophic factor (BDNF) and glial cell-derived neurotrophic factor (GDNF), involved in recovery after stroke." (PMID 41155363, 2025). "In stroke models, direct GDNF infusion significantly increases neurogenesis in the striatum, while in the hippocampus, GDNF and its receptor GFRα1 are essential for proper integration of adult-born granule neurons." (PMID 40642294, 2025). "Here, we demonstrated the presence of AQP4 and GDNF in ADEV cargo during the first month following stroke, expanding on our previous findings regarding the post-ischemic ADEV profile and the GFAP content of these vesicles." (PMID 39596535, 2024). "GDNF expression is upregulated in Ras after stroke, and RAs-derived GDNF plays an important role in neuronal protection and brain recovery." (PMID 37704780, 2024). "We performed Western blotting on the protein lysates from the total extracellular vesicle (TEV) and ADEV aliquots to detect and quantify the AQP4 and GDNF in EV cargo from the stroke-related samples compared to the control group." (PMID 39596535, 2024). "These secondary RCT outcomes represent the first multi-session study to evaluate the effects of chiropractic adjustments on serum BDNF, IGF-II and GDNF in people with stroke." (PMID 36556107, 2022). "For preclinical studies in a mouse PD model, a TfRMAb–GDNF fusion protein was engineered, and this fusion protein was neuroprotective in both experimental PD, and experimental stroke following delayed IV administration in the mouse." (PMID 35745855, 2022). "Herein, our scope was investigating the possible impact of GDNF treatment on striatal dopaminergic neurons in the acute phase of stroke." (PMID 34773698, 2022). "Other mechanisms: Astrocytes can also release several neuroprotectants, including erythropoietin (EPO), VEGF, and glial-derived neurotrophic factor (GDNF), all of which can reduce ischemic neuronal damage after stroke." (PMID 35743941, 2022). "Our finding indicated that baseline serum CRP, GDNF, IFN-γ, IGFBP-6, IL-4, LYVE-1, MMP-2, PAI-1, and PDGF-AA levels were associated with post-thrombolytic sICH in stroke." (PMID 35173671, 2022). "Neurotrophic factors, such as brain-derived neurotrophic factor (BDNF) and glial cell line-derived neurotrophic factor (GDNF), are considered to be involved in the regulation of key nerve functions and neuroplasticity in stroke." (PMID 35221926, 2022). "PEA was able to prevent the plasmatic reduction of the brain-derived neurotrophic factor (BDNF) and glial cell line-derived neurotrophic factor (GDNF) in a murine model of stroke, thus explaining, at least in part, its neuroprotective effects." (PMID 35740883, 2022). "To date, no studies have evaluated the effects chiropractic care on serum brain-derived neurotrophic factor (BDNF), insulin-like growth factor-II (IGF-II) and glial cell-derived neurotrophic factor (GDNF) in people with stroke." (PMID 36556107, 2022).
Stroke (continued). "BDNFs and glial-derived neurotrophic factors (GDNF) increase the functional outcomes of and recovery from strokes." (PMID 34903913, 2021). "Delta opioid peptide [D‐ala2,D‐leu5] enkephalin (DADLE) increased GDNF expression and protected against cell death in stroke brain." (PMID 34018697, 2021). "Ntera2 cells transplanted into stroke lesioned rats show the ability of these cells to secrete glial cell line-derived neurotrophic factor (GDNF) and lead to an improvement in sensorimotor function via neuronal rescue." (PMID 34572529, 2021). "In another study, GDNF expressing NSCs were administrated via the same approach and into the ipsilateral lateral ventricle of stroke model rats, and improved neurogenesis in the marginal zone of ischemic striatum was obtained." (PMID 34641969, 2021). "Application of GDNF producing NSCs in stroke model rats triggered neurogenesis and Erk1/2 phosphorylation while the expression of MKP-1 was reduced." (PMID 34641969, 2021). "As an important neurotrophic factor, glial cell-derived neurotrophic factor (GDNF) can reduce the area of infarction during the acute stage of stroke." (PMID 32670064, 2020). "Ginsenoside Rb1 can upregulate the expression of GDNF to inhibit neuron apoptosis and promote motor function recovery and axon regeneration in mice after stroke through the cAMP/PKA/CREB signaling pathway." (PMID 33294469, 2020). "Intrathecal transplantation of the gene–cell construct (UCB-MC+Ad-VEGF+GDNF+NCAM) 4 h after distal occlusion of MCA in rat revealed gene modified cells in the stroke area 3 weeks after transplantation." (PMID 29497380, 2018). "The comparative analysis of direct gene therapy, cell therapy, and cell-mediated gene therapy for stroke in rat model revealed the superiority of triple gene (VEGF+GDNF+NCAM) therapy over UCB-MC therapy." (PMID 29497380, 2018). "The GDNF increase was attributed to D1R-expressing reactive astrocytes which appear in the peri-infarct region around 7 days following stroke." (PMID 30034335, 2018). "Over expression of some neuroprotective cytokines including VEGF, neurotrophin-3, BDNF, FGF-2, and GDNF has been reported to potentiate the therapeutic effects of transplanted NSCs in stroke animals." (PMID 24719869, 2014). "Engraftment of CPs in adult stroke models reduced infarct size and improved neurological function, in part via secretion of glial cell line-derived neurotrophic factor (GDNF), brain-derived neurotrophic factor (BDNF), and nerve growth factor (NGF)." (PMID 25426016, 2014). "It is likely that DADLE-mediated GDNF upregulation had already been in place even prior to stroke, since DADLE was administered repeatedly starting at 6 h pre-stroke." (PMID 19534760, 2009). "The mechanism we proposed for the observed protective effects of DADLE is the ability of DADLE to increase expression of GDNF in the striatum and cortex, which are the MCAor stroke target brain areas." (PMID 19534760, 2009). "Our pre-stroke DADLE paradigm is in agreement with previous studies reporting that optimal GDNF therapeutic effects are achieved when initiated at an ample time interval prior to injury." (PMID 19534760, 2009). "Recent studies have shown that the intracerebral injection of MSCs transfected with the BDNF or GDNF gene resulted in improved function and reduced ischemic damage in a rat stroke model of middle cerebral artery occlusion." (PMID 18060066, 2007). "A study conducted on animal models of stroke reported that muscle GDNF signalling in the nervous system might play a key role in pain-related behaviours and exercise-mediated reflexes." (PMID 40141452, 2025). "However, another study reported a decrease in GDNF of stroke patients compared to controls with cerebrovascular disease." (PMID 39596535, 2024). "The GDNF trophic effects of the HIRMAb-GDNF fusion protein were also tested in an in vivo bio-assay using the middle cerebral artery occlusion (MCAO) model of stroke in rats." (PMID 38035276, 2023).